EPHB2 (EPH receptor B2)
Diseases named in the same sentence as EPHB2 in open-access papers (continued):
Sharing a sentence is not in itself a finding about the gene and the disease.
tumor (continued). "Finally, a combined expression of EphA2, EphA3, EphB2 and IL-13RA2 is observed in almost every GB patient, presenting in tumor-infiltrating cells, tumor-initiating cells or GSCs and neovasculature." (PMID 34209513, 2021). "EphB2 has emerged as a candidate for therapeutic strategies to prevent GB tumor invasion." (PMID 34209513, 2021). "Additionally, CRC patients with lower EphB2 expression were found to have more advanced tumor stages, poor differentiation, poor overall survival, and poor disease-free survival." (PMID 34360867, 2021). "However, EphB2 staining was accumulated in pseudostratified intestinal glands (in both types of tumor) and in Paneth cell-positive samples containing high nuclear β-catenin, being monolayered glands EphB2 negative." (PMID 34831152, 2021). "This made us reconsider our initial hypothesis that EphB2 might be a bona fide tumor suppressor, and that it might rather possess a dual context-dependent function, mainly modulated by co-expression of cognate ephrin ligands." (PMID 34360867, 2021). "Moreover, it was observed as the spreading of intestinal EphB2-EphB3-positive tumor cells was hampered by the interaction with surrounding ephrin-B1-expressing normal cells, which led to the reinforcement of E-cadherin adhesion." (PMID 32316101, 2020). "And activation of the EphB2 gene expression elevated the levels of migration and invasion, but suppressed adhesion of GC cells, indicating that EphB2 may act as a tumour promotor in GC." (PMID 32226496, 2020). "Moreover, FOXA1, FOXA2, and FOXA3 were also grouped together with the tumor/invasion suppressor genes EPHB2 and EPHB3, and with the intestine-specific differentiation genes CDX1 and CDX2 (cluster 2)." (PMID 29155818, 2017). "For instance a recent study proposed that EPHB6 could decide the fate of the tumor by interacting with other receptors such as EPHB2 and EPHA2." (PMID 26870995, 2016). "Interestingly, EPHB2 has been shown to have a pro-invasive role also in other tumor models, such as in GBM, where on the other side it shows anti-proliferative actions, suggesting a dichotomic role." (PMID 27058903, 2016). "To confirm that EphB2-high cells may be enriched for CSCs, we performed tumor sphere formation assay." (PMID 27833077, 2016). "EPHB2 was found in the cell membrane and the cytoplasm of the tumor cells." (PMID 26870995, 2016). "Collectively, our data suggest that ephrinB2 loss promotes tumour invasion by increasing the intrinsic invasive capacity and by permitting the invasion into the EphB2/EphB4 expressing parenchyma through avoiding repulsive interactions, thereby reducing tumour compartmentalization." (PMID 27470974, 2016). "We sought to investigate whether the contrasting expression pattern of ERBB3 and EPHB2 was conserved in multiple tumours or if some tumours contained cells which co-expressed both markers." (PMID 26367378, 2015). "The sensitivity of our tumor line to ephrin ligand and the changes induced by EphB2 activation uncovered the possibility that receptor activation may affect other tdNSC traits." (PMID 25801123, 2015). "However, co-immunofluorescence analysis showed that ERBB3 and EPHB2 marked specific cell populations that were mutually exclusive within tumours with distinct proliferative potentials, the majority of ERBB3+ve cells being non-proliferative." (PMID 26367378, 2015). "In contrast, in the same tumour, EPHB2+ cells were mainly positive for KI-67." (PMID 26367378, 2015). "Furthermore, 16 of the 18 tumor (89%) specimens showed an EphB4 signal, while 0 of 18 (0%) stained for EphB2." (PMID 25148033, 2014). "In addition, decreased cell growth has been observed in EphB2-expressing tumor cells in the presence of the EphrinB1/Fc ligand." (PMID 24959213, 2014). "The cells that were expressing higher levels of EphB2 exhibited more effective tumor growth inhibition as a result of the QYHJ treatment, therefore, EphB2 may function as an effective predictive factor for QYHJ treatment." (PMID 24959213, 2014).
tumor (continued). "In general, EPHB2 function depends on the tumor type and signaling context of the neoplastic cell." (PMID 22613809, 2011). "In addition, premalignant lesions of the colon were shown to express high levels of EPHB2, whereas the expression was reduced in more advanced tumor stages." (PMID 16740153, 2006). "However, high EPHB2 expression was associated with improved overall survival in CRC, suggesting that EPHB2 may affect long-term outcomes via protective roles in tumor biology or therapeutic response." (PMID 40958237, 2025). "Furthermore, it was noted that tumor grade increased as EphB2 levels decreased." (PMID 39839790, 2024). "Genetic analysis of a cohort of 50 CRC samples revealed no mutations, indicating that EPHB2 may play a role in CRC development but is not a classical tumor suppressor gene." (PMID 38651144, 2024). "EPHB2 can function as both tumor promoter and suppressor in different cellular contexts and is downregulated in our dataset, a finding that correlates with reports showing that inactivation of EPHB2 promoted cell proliferation and invasion in certain types of cancers." (PMID 37685904, 2023). "In immunocompetent mouse models, targeting EPHB2 with rAAV-8-shEPHB2 (EPHB2 inhibitor) inhibited HCC tumor growth and sensitized HCC cells to sorafenib, indicating that targeting tumor cell stemness may be a feasible therapeutic strategy against sorafenib resistance in HCC." (PMID 36891274, 2023). "Moreover, knockout of endogenous EPHB2 showed reduced tumor growth in mice." (PMID 35223830, 2022). "Furthermore, EPHB2 was positively correlated with tumor stage." (PMID 34445116, 2021). "From these data, along with in vitro and in vivo results, we conclude that EphB2 is moderately expressed and might behave as a tumor suppressor in normal and benign mammary tissues, despite being overexpressed in later stages, when it is associated with invasiveness and metastasis." (PMID 34360867, 2021). "In other words, increases in EphB2 levels might result in distinct functions depending on the cellular and molecular context and patient therapeutic history, rather than being of an overall fixed and linear pattern throughout tumor progression." (PMID 34360867, 2021). "Moreover, miR-204 acts as a tumor suppressor in the metastasis of CC by directly targetting Ephrin type B receptor 2 (EphB2), which might promote the progression of tumors by inducing EMT and affecting its major downstream signaling pathway, PI3K/AKT." (PMID 30833362, 2019). "Additionally, we observed substantial differences in the phosphorylation state of several key proteins involved in Ras and p38 MAPK signaling when comparing EphB2 overexpressing Ink4a/Arf(−/−) STeNSCs and tumor cells with relatively little change in total protein levels." (PMID 25801123, 2015). "Surprisingly, while EphB2 overexpressing cells have a similar profile for a minimum of two months post-implantation, a sharp increase in signal intensity and change in animal phenotype (domed skull, hunched posture, thin appearance and lethargy) always follows, indicating tumor growth." (PMID 25801123, 2015). "EphB2 is also stabilized under hypoxia by HIF-2α and promotes GBM cell invasion via paxillin phosphorylation, suggesting a HIF-2α-EphB2-paxillin axis that supports epithelial-mesenchymal transition (EMT) and tumor aggressiveness." (PMID 41200151, 2025). "Our results regarding EPHB2 and LGR5 stem-cell signatures support the importance of periostin for cancer stem-cell niches at the pericryptal regions for tumour development." (PMID 38532103, 2024). "ADEM10, EPHB2, HDAC4, and SEPP1 in CRC inhibit cell migration, invasion, tumor growth, and liver metastasis through the SP1." (PMID 36798788, 2023). "In tumor-to-stroma signaling, primary and metastatic lesions are characterized by EFNA2 interacting with EPHA1, EFNB3 interacting with EPHB2, and EFNB3 interacting with EPHB6, among several others." (PMID 36676129, 2023).
tumor (continued). "EPHA4 and EPHB2 were significantly enriched in the BTY25 line, suggesting a tumor potentially driven by Ephrin receptors." (PMID 36077757, 2022). "In this study, EFNA3, EFNB1, EFNB2, and EPHB2 showed a significant correlation with OS and PFS in LUAD patients and were differentially expressed in tumor tissues and normal lung tissues." (PMID 34645436, 2021). "For instance, tumor-initiating cells are characterized by bona fide expression of normal stem cell markers such as LGR5 and EPHB2 in CRC." (PMID 33498251, 2021). "EphB2 overexpression in GBM has been reported to drive invasion and migration of the tumor cells via the focal adhesion kinase (FAK) pathway." (PMID 32340173, 2020). "Tumor growth and the mRNA expression of lncRNA AB209630, miR373, EphB2, and NANOG evaluated in dissected tumor tissue by real-time PCR, the CD133+ cancer stem cells were isolated by flow cytometer, and the changes of the tumor sphere forming were measured." (PMID 31147453, 2019). "In order to determine the mechanism of QYHJ on GEM resistant tumor tissue, we detected the mRNA expression of lncRNA AB209630, miR-373, EphB2, and NANOG in tumor tissue." (PMID 31147453, 2019). "QYHJ, especially GEM + QYHJ treatment, was significantly increased the mRNA expression of lncRNA AB209630, significantly decreased the mRNA levels of miR373, EphB2 and NANOG, and markedly reduced the tumor sphere formation and the numbers of CD133+ stem cells." (PMID 31147453, 2019). "MiR-10b overexpression accelerated PCC proliferation and tumor growth; miR-10b enhanced the stimulatory effects of EGF and TGF-β on cell migration and EMT, decreasing the expression of RAP2A, EPHB2, KLF4 and NF1." (PMID 29254283, 2017). "CSC-like cells were independently isolated from CRC cells using CD133, CD44 or EphB2-high as markers and the features of these cells as CSC-like cells were proven by tumor sphere formation assay." (PMID 27833077, 2016). "Following co-immunofluorescence and image analysis, the number of P-H3+ cells in the four different cell populations (EPHB2+/ERBB3+; EPHB2+/ERBB3-; EPHB2-/ERBB3+; EPHB2-/ERBB3-) was quantitated (between 100–200 P-H3+ cells per tumour)." (PMID 26367378, 2015). "Most importantly, and as observed in the primary tumours, the expression of ERBB3 and EPHB2 was positively correlated (Pearson correlation test, rho = 0.999, p<0.0001)." (PMID 26367378, 2015). "The results showed that tumor weight was 0.14±0.04, 0.16±0.04 and 0.40±0.10 g for CFPAC-1, CFPAC-1 control RNAi and CFPAC-1 EphB2 RNAi cells, respectively, and the tumor weight inhibitory rate was 31.40, 31.33 and 18.36%, respectively." (PMID 24959213, 2014). "The results showed that the tumor weight inhibitory rate was 31.40, 31.33 and 18.36% in CFPAC-1, CFPAC-1 control RNAi and CFPAC-1 EphB2 RNAi cells following QYHJ treatment, respectively." (PMID 24959213, 2014). "In the QYHJ group, tumor weight was 0.14±0.04, 0.16±0.04 and 0.40±0.10 g for the CFPAC-1, CFPAC-1 control RNAi and CFPAC-1 EphB2 RNAi cells, respectively." (PMID 24959213, 2014). "The results showed that the mRNA and protein levels of EphB2 changed indistinctly, following QYHJ treatment, in the CFPAC-1, CFPAC-1 control RNAi and CFPAC-1 EphB2 RNAi cells of the subcutaneous tumor." (PMID 24959213, 2014). "The expression of OLFM4, EPHB2, and ASCL2 was relatively restricted to the basal region of tumor glands in the GA with basal LGR5 expression, but the expression of these markers was diffuse in the GA with a diffuse LGR5 expression pattern." (PMID 24340024, 2013). "EphB2 was identified as one of the signature tyrosine kinases of the BL2 subtype, which could lead to novel approaches for tumor diagnosis and targeted therapy." (PMID 40943224, 2025). "We also note > two-fold increased expression in some members of the Ephrin pathway (EPHA10, EPHB1, EPHB2, EPHB3) that may play key roles in tumor progression, invasion, and immune evasion." (PMID 38704802, 2024).
tumor (continued). "Next, the in vitro experiments revealed that the tsRNA-GlyGCC inhibitor suppresses cell proliferation, migration, and formation of tumor spheres by modulating the protein expression of BCL2, BAX and cancer stem cells molecular markers (CD44,CD133, EphB2, LICAM, and LGR5)." (PMID 39153969, 2024). "Here we show that humanized ISC signature scores (Hu-EphB2-ISC; Hu-Lgr5-ISC), but not non-stemness signature scores such as Hu-Late TA and Hu-Proliferation, were significantly associated with tumor progression in 2191 Stage I-IV (primary) and metastatic CRCs." (PMID 35272617, 2022). "For each tumor, we generated multiple gene expression signature scores measuring MEK pathway activation, MEKi “bypass” resistance, SRC activation, dasatinib sensitivity, EMT, PC1, Hu-Lgr5-ISC, Hu-EphB2-ISC, Hu-Late TA, Hu-Proliferation, and WNT activity." (PMID 35272617, 2022). "The expression levels of the EphB2 protein in the tumour tissues of tissue arrays were higher than the benign non-cancerous gastric tissues (P<0.05)." (PMID 32226496, 2020). "The presence of cells that co-expressed EPHB2 and ERBB3 was rare (2.1% tumour cells)." (PMID 26367378, 2015). "One tumour was characterised by the absence of EPHB2+ cells and presence of a large population of double negative cells (EPHB2-/ERBB3-, 85.1% of cancer cells)." (PMID 26367378, 2015). "Even though the survival curve of EphB2(ΔSAM/PDZ) implants appears to have a longer tumor latency than wild-type EphB2, it was not statistically significant (203 vs. 289 day median survival for EphB2 vs. EphB2(ΔSAM/PDZ) respectively)." (PMID 25801123, 2015). "While tumor-specific and active in forward signaling, EphB2 does not appear to function as a primary oncogenic driver, suggesting that targeting both receptor and ligand may be necessary to disrupt its pro-invasive effects." (PMID 41200151, 2025). "Additionally, we observed that mATC cells overexpressed receptors such as FGFR1, EPHB2, PDGFRA, NOTCH3, ANTXR1, and NRP1, which could receive signals from CAFs and thereby promote tumor cell proliferation and aggressiveness." (PMID 37053016, 2023). "Thus, ephrin-A5 could have been investigated as a potential tumor-suppressing ligand through the interaction with its tumor promoting receptors such as EPHA2, EPHA3, EPHA4, EPHA5, EPHA7, EPHA8, and EPHB2 in sarcomas." (PMID 35563562, 2022). "By IHC analysis, we detected EphB2 staining in both Paneth cell-positive and -negative samples (determined by detection of eosin-positive granules) with some accumulation in Paneth cell-negative tumor samples." (PMID 34831152, 2021). "Multiple evidence indicates that tumor-initiating cells depend on the same signaling pathways that regulate normal ISC function including Notch, Wnt//β-catenin and TGF-β, through activation of a stem cell transcriptional program containing genes such as Lgr5, Bmi1, EphB2 or Hes1." (PMID 34831152, 2021). "However, a sub-group of EPHB2-/ERBB3+ cancer cells were not positive for MUC2 in these tumours (white arrows)." (PMID 26367378, 2015). "However, tumor formation was not seen when the inactive EphB2(K662R) (7/7) mutant (dash line) and EphB2-ΔLBD(C-Term-His) (data not shown; 8/8) receptors were overexpressed, further support for the requirement of receptor activation in tumor formation." (PMID 25801123, 2015). "EphB2 expression in the tumor samples had no or low levels of EphB2 compared to the normal bladder." (PMID 25148033, 2014). "The same analysis was not performed for EphB2 because EphB2 expression is lost in tumor." (PMID 25148033, 2014). "A number of genes demonstrated reduced copy number and expression in KRAS mutant tumours, including putative tumour suppressor genes (FOXO3, EXTL2, PPP2R1B), negative regulators of the receptor tyrosine kinase oncogenic pathways (PTPRK, DGKZ, NCAM1), and negative regulators of Ras (EPHB2)." (PMID 21385341, 2011).
tumor (continued). "Finally, the gene-set #2 also contained several tumour suppressors (EPHA3 and EPHB2) and proto-oncogenes (AKT1, AURKA, ETV6, MITF and PIK3CA), which expands on the observed enrichment of the immune response and suggests that this gene-set has a critical role in breast tumorigenesis." (PMID 19826428, 2009). "The father's tumor manifested LOH of the variant, rather than the wild-type, EPHB2 allele." (PMID 18682749, 2008). "EphB4 provides a survival advantage in tumor cells by further activating the PI3K pathway, unlike EphB2, which is expressed in normal gland and functions as a tumor suppressor." (PMID 40044981, 2025). "EPHB2 expression levels were significantly higher in stage III, but not stage IV, tumours compared to stage I tumours (Coefficient = 1.47 (95% CI 0.30, 2.64), p = 0.015)." (PMID 26367378, 2015).